IL6 (interleukin 6)
Diseases named in the same sentence as IL6 in open-access papers (continued):
Sharing a sentence is not in itself a finding about the gene and the disease.
COVID-19 (continued). "In diesem Zusammenhang sind mögliche positive Einflüsse auf die COVID-19-Schwere auch durch Interferon‐β (antivirale Wirkung) oder monoklonale Antikörper gegen den Interleukin-6-Rezeptor (Tocilizumab) beschrieben worden." (PMID 34232359, 2021). "A recent meta-analysis reported that mean IL-6 concentrations raised to nearly threefold higher in complicated versus uncomplicated COVID-19 patients and 9 out of 10 studies examined showed elevated IL-6 levels associated with worse prognosis." (PMID 34176095, 2021). "Many proinflammatory cytokines were found to be significantly increased in critically ill COVID-19 patients, but elevated levels of IL-6 were the most frequently detected." (PMID 34829920, 2021). "introduced Baricitinib, a JAK kinase inhibitor, to be trialed in COVID-19 patients as it showed inhibitory properties against IL-6 and STAT3 phosphorylation and is approved for treatment of rheumatoid arthritis." (PMID 34659259, 2021). "Elevated levels of IL-6 in the blood have been reported to be predictive of a fatal outcome in patients with COVID-19." (PMID 34428204, 2021). "In COVID-19, some of the dysregulated pro-inflammatory cytokines (IL-1β, IL-6, and IL-8) play a pathological role in promoting platelet activation and causing platelet dysfunction." (PMID 34945800, 2021). "In conclusion, both active AOSD and severe COVID-19 patients showed elevated Gal-3, Gal-9, and cytokines, including IL-1β, IL-1Ra, IL-10, IL-6, IL-18, and TNF-a, supporting a common link of cytokine storm in the pathogenesis of both diseases." (PMID 34367188, 2021). "In particular, we found that IL-6 levels were significantly higher in MIS-C (133.8 pg/ml) than COVID-19 (5.22 pg/ml) (p = 0.043)." (PMID 33841438, 2021). "Depression and COVID-19 demonstrate shared patterns of immunological function, especially around a pro-inflammatory state characterized by elevation in cytokines including IL-6, TNFα, and IL-1β." (PMID 33967944, 2021). "Tocilizumab (which blocks IL-6 signaling) was administered to treat the hyperinflammation of critical COVID-19 obese patients during the first days of worsening hypoxemia." (PMID 34777390, 2021). "Existing evidence has suggested a correlation between high IL-6 levels and the progression of COVID-19 severity." (PMID 34123873, 2021). "The difference is likely due to higher peak levels of IL-6; 27,651.1 pg/mL measured herein and elsewhere compared to COVID-19; ≤250 pg/mL." (PMID 34452463, 2021). "The percentage of CD16Int LDNs, however, showed a significant positive correlation with TNF-α and IL-6 levels across all COVID-19 patients." (PMID 33986193, 2021). "IL-6 levels in COVID-19 patients are a strong predictor of mortality and lung damage, and it has been suggested as a key therapeutic target in COVID-19 associated pathologies." (PMID 34566657, 2021). "Previous studies had reported that IL-6 positively correlated with the severity of COVID-19, with higher levels of IL-6 present in patients with severe and critical COVID-19 than those present in patients with common illness." (PMID 33937333, 2021). "Increases in lactate dehydrogenase, C-reactive protein (CRP), D-dimer, ferritin and interleukin-6 (IL-6) are common laboratory findings in patients with COVID-19." (PMID 33670475, 2021). "Serum levels of IL-7, IL-10 and IP-10 were elevated in COVID-19 asymptomatic cases compared to healthy controls, whereas IL-1RΑ, IL-1β, IL-6 and IP-10 were higher in symptomatic compared to asymptomatic COVID-19 patients." (PMID 34603318, 2021). "Analyses performed in the BAL fluids showed that the chemokines CCL3 and CCL5 and the proinflammatory molecules IL-1β and IL-6 were significantly higher in patient 1 compared to the non-COVID-19 bLTx patient." (PMID 33801959, 2021).
COVID-19 (continued). "Cytokine storm was well-described in patients with severe COVID-19, displaying significantly elevated serum levels of IL-6, IL-8, IL-10, IL-2R, and tumor necrosis factor-alpha (TNF-α) compared with those mild and moderate patients." (PMID 35155477, 2021). "In COVID-19 patients higher LDH, CRP, IL-6, and D-dimer values were associated with longer lag-time triggered by TF." (PMID 33833254, 2021). "Nevertheless, studies have been performed to investigate the possible benefit of IL-6 antagonists in COVID-19 patients with serious symptoms." (PMID 34835296, 2021). "The analysis of clinical data revealed a markedly increased neutrophil count, lymphopenia, increased neutrophils-to-lymphocytes ratio and neutrophils-to-lymphocytes CD4+ ratio, and elevated CRP, LDH, and IL-6 concentrations in critically ill COVID-19 patients." (PMID 34445556, 2021). "During the acute response, interleukin-6 (IL-6) is key and has been consistently observed in high levels among patients with severe COVID-19 outcomes and generic hyperinflammatory phenotype." (PMID 33651876, 2021). "These cytokines changed like those of patients with COVID-19, and IL-6 and IFN-γ were significantly upregulated upon SARS-CoV-2 challenge." (PMID 33692211, 2021). "Cytokines such as TNF- α, CCL2, CXCL8, and IL6, which show high levels in COVID-19 patients requiring ICU admission, can predictably be inhibited by the bioactive components." (PMID 34513735, 2021). "Many of the cytokines that were overexpressed in our research cohorts, including IL1 and IL6, were identified as COVID-19 related CSS proteins." (PMID 35145507, 2021). "Furthermore, in hyperglycaemic patients, higher plasma IL-6 levels were associated with reduced effects of tocilizumab, indicating that hyperglycaemia may cause exaggerative and harmful inflammation in patients with COVID-19." (PMID 33771154, 2021). "IL-6 is not only the main therapeutic target for the treatment of COVID-19 complicated by cytokine storm syndrome, it is also a pro-fibrotic factor produced in the Th2-type immune response." (PMID 35069217, 2021). "There were 5 KEGG pathways with IL6 involvement in the first 5 KEGG pathways in which the junction targets of COVID-19 and LHQW were involved (P ≤ 0.05)." (PMID 34731090, 2021). "Of note, the synthesis of IL-6 induces the production of CRP, which is considered to be one of the first biomarkers associated with cytokine storm among COVID-19 patients." (PMID 35056328, 2021). "sTREM-1 and IL-6 represent different aspects of the inflammatory response, but are both involved in the dysregulated inflammatory state seen in COVID-19 and sepsis patients." (PMID 34195785, 2021). "The role of systemic inflammation in augmenting musculoskeletal pain, however, is also a likely contributing factor, particularly given the elevated levels of known nociceptive mediators, such as interleukin-6 (IL-6) in the sera of patients with COVID-19." (PMID 33458558, 2021). "Prebiotics reportedly reduce the levels of the proinflammatory IL-6 that tends to be the prime culprit behind the hitherto described grave prognosis in COVID-19 and enhance the levels of anti-inflammatory IL-10." (PMID 33791231, 2021). "Proteomics analysis revealed the up-regulation of iNOS and IL1b and IL6 proteins in lung tissue of COVID-19 patients [TE113]." (PMID 34876157, 2021). "Elevated IL6 levels are found in COVID-19 patients with mild and severe symptoms implying that IL6, alongside other cytokines, can be of prognostic value in these patients." (PMID 34451985, 2021). "Ferritin synthesis can be stimulated by several inflammatory cytokines, including interleukin-6 (IL-6), which has been specifically targeted in COVID-19." (PMID 34362074, 2021).
COVID-19 (continued). "However, specific variants of genes (e.g., ACE2, TMPRSS2, and interleukin-6 (IL-6)) or the differential expression of related genes may explain the individual differences in the sensitivity and severity of COVID-19 by altering the kinetics of the viral interaction and endocytosis." (PMID 33404925, 2021). "Specifically, minocycline is effective in reducing COVID-19–related complications, through attenuation of cytokine storm as apparent by reduction of interleukin (IL)-6, IL-1, and tumor necrosis factor (TNF)-α." (PMID 33967777, 2021). "Consistent with published studies, we observed high concentrations of inflammation-associated cytokines, including IL-6, TNF-α, IP-10, IL-10, IL-1α and IL-1β, in serum and nasal lining fluid from PCR-confirmed COVID-19 patients." (PMID 34117221, 2021). "Collectively, combining IL-6 level and SARS-CoV-2 RNA copy number in peripheral blood allowed before intubation identifying COVID-19 patients at high risk for fatal outcomes after MV use, including ECMO use and in-hospital death." (PMID 34379684, 2021). "PMN-MDSC expanded during COVID-19 in patients who required intensive care treatments, and correlated with IL-1beta, IL-6, IL-8, and TNF-alpha plasma levels." (PMID 34220859, 2021). "Results showed that the AUC of the ROC curve was 0.774 for IL-6 (P < 0.001), the optimal cut-off value for IL-6 concentration was 6.735 pg/mL, and the sensitivity and specificity to predict the severity of COVID-19 were 76.7% and 76.6%, respectively." (PMID 33390771, 2021). "This process is followed by activation of the IL-6 amplifier (IL-6-AMP), which co-activates NF-κB and transcription factor STAT3 to enhance inflammatory response and leads to ARDS underlying COVID-19." (PMID 33503821, 2021). "We noticed correlation in the severe COVID-19 group between cytokines IL-6 and IL-10 levels and neutrophils, what was reported by other studies." (PMID 34064802, 2021). "Elevated levels of IL-6 are a good marker of poor outcomes in patients with severe COVID-19 with pneumonia and acute respiratory distress syndrome (ARDS)." (PMID 34680053, 2021). "Proinflammatory cytokines levels (IL-6, IL-8) in hyperinflammatory ARDS were at least 20-fold higher than hyperactive COVID-19 in our study, suggesting that COVID-19 is associated with only mild inflammatory cytokine elevation." (PMID 34150812, 2021). "Among many cytokines discussed hereafter IL-6 also regulates coagulation likely contributing to COVID-19 thrombosis related mortality." (PMID 34326843, 2021). "Despite direct viral effect, the pathogenesis of coronavirus disease 2019 (COVID-19) includes an overproduction of cytokines including interleukin 6 (IL-6)." (PMID 33918563, 2021). "Future studies should particularly focus on the practical clinical value of HMGB1 and IL-6, including developing a scoring system with plasma HMGB1 and IL-6 as biomarkers for early recognition of COVID-19 patients at risk for developing severe disease." (PMID 33939645, 2021). "BTK is a known regulator of macrophage activation, and treatment of COVID-19 patients with acalabrutinib has been shown to improve oxygenation as well as normalization of IL-6 levels." (PMID 33467724, 2021). "Recently, IL-6 has been considered as a factor that exacerbates the symptoms of coronavirus disease (COVID-19)." (PMID 34576053, 2021). "IL-6 and IL-12p70 were the most discriminant cytokines for COVID-19 and controls, respectively, as confirmed by their pairwise analysis." (PMID 34394024, 2021). "Among them, IL-6 is an important factor found elevated during the pathology of COVID-19 with a cytokine storm." (PMID 34908920, 2021). "Critical COVID-19 patients also showed high levels of several proinflammation cytokines, such as IL-2R, IL-8, and IL-6, and anti-inflammatory IL-10, as described by a previous report." (PMID 34712742, 2021). "Several studies have revealed that IL-6 plays a key role in cytokine storm and that serum IL-6 levels correlate with the severity of COVID-19." (PMID 33011959, 2021).
COVID-19 (continued). "It is necessary to systematically evaluate and update the effects of IL-6 inhibition among COVID-19 patients as new data are generated." (PMID 34001244, 2021). "Meanwhile, previous studies showed that patients with COVID-19 were in a pro-inflammatory status with high levels of IL-1β and other cytokines, and high levels of IL-6 and TNF-α were observed in COVID-19 patients requiring intensive-care-unit hospitalization." (PMID 34863291, 2021). "The therapeutic efficacy of SHXP against COVID-19 is likely mediated via the regulation of 4 targets, namely, IL6, IL10, VEGFA, and TNF." (PMID 34941025, 2021). "Most importantly, terminally ill patients with elevated IL-6 levels succumb to COVID-19 more readily than survivors." (PMID 34356617, 2021). "Tocilizumab, a recombinant humanized monoclonal antibody that targets the soluble and membrane-bound IL-6 receptor to inhibit IL-6 signaling, is used for the treatment of various inflammatory diseases and more recently COVID-19 and MIS-C." (PMID 33897686, 2021). "Yet, the clinical results of IL-6 blockade with siltuximab or tocilizumab are varied in COVID-19 patients." (PMID 34945111, 2021). "Previous studies showed that the elevation of serum IL-6 was considered to be related with the severity of COVID-19." (PMID 34725309, 2021). "Human cells respond to infection by SARS-CoV-2, the virus that causes COVID-19, by producing cytokines including type I and III interferons (IFNs) and proinflammatory factors such as IL6 and TNF." (PMID 34211037, 2021). "Laboratory-confirmed patients with COVID-19 with an elevated interleukin-6 (IL-6) level (>10 pg/ml) were offered TCZ intravenously for compassionate use." (PMID 33937333, 2021). "For example, increased level of IL-6 has been considered as a predictor of poor outcomes in COVID-19 patients, because of the fact that IL-6 is indeed one of the most accurate aging indicators." (PMID 35822018, 2021). "Related clinical studies have found that IL-6 levels in severe COVID-19 patients were much higher than in healthy population." (PMID 37287491, 2021). "Highly activated inflammatory immune responses, including Interferon-gamma (IFN-γ), interleukin-6 (IL-6), and NF-κB responses, had been reported in COVID-19 patients." (PMID 34697287, 2021). "Similarly, profound inflammation, as indicated by increased levels of the cytokines tumor necrosis factor (TNF)-α, IL-1, and IL-6, leading to cochlea cell stress, has been implicated in the sudden irreversible sensorineural hearing loss that occurred in a patient with severe complicated COVID-19." (PMID 34066007, 2021). "A plethora of studies has shown that the elevation of IL-2 and IL-6 is correlated with COVID-19 replication and disease severity and that patients requiring ICU admission had higher concentrations of cytokines than those who were not requiring ICU admission." (PMID 34176479, 2021). "A recent review summarized the roles of IL-6 in COVID-19 pathogenesis and highlighted the important therapeutic potential of the IL-6 blockade in COVID-19 management." (PMID 33465050, 2021). "As expected, several cytokines and chemokines were significantly elevated in COVID-19 patients (mild and severe) compared with HCs (HC and HC-CoV-2 Ab+), including interleukin 6 (IL-6)." (PMID 34619366, 2021). "EAT is an inflammatory depot with conspicuous macrophage infiltrates and proinflammatory cytokines, such as interleukin-6 (IL-6), which is secreted by numerous cells (monocytes, fibroblasts, endothelial cells, adipocytes), overexpressed in COVID-19 patients." (PMID 33995281, 2021). "We show that in COVID-19, IL-1β and IL-6 cytokine activity is detectable at a site of disease, the nasopharynx, where greater IL-6 bioactivity in particular is associated with higher levels of SARS-CoV-2 detected." (PMID 33319166, 2021).
COVID-19 (continued). "Coffee consumption favorably correlates with inflammatory biomarkers such as CRP, interleukin-6 (IL-6), and tumor necrosis factor α (TNF-α), which are also associated with COVID-19 severity and mortality." (PMID 34203027, 2021). "A prospective cohort study involving 102 COVID-19 from Renmin Hospital, Wuhan, China, compared with 45 healthy controls, illustrated that IL-6 and other pro-inflammatory cytokines are higher in COVID-19 patients than controls." (PMID 34806090, 2021). "We performed a subset analysis of interleukin 6 (IL-6) levels with QTc maximum in patients with COVID-19 (eFigure 3 in the Supplement)." (PMID 33890991, 2021). "This study reported that patients recovering from COVID-19 had significantly decreased sperm concentration and increased seminal interleukin 6 (IL-6), TNF-α, and monocyte chemoattractant protein-1 (MCP-1) compared to control." (PMID 34552795, 2021). "In line with prior reports, IL-6 was ~1 log higher in COVID-19 patients compared with HVs, with the highest levels noted in the most severely ill patients." (PMID 33232303, 2021). "All biological DMARDs (bDMARDs) except for IL-6 inhibitors and all targeted synthetic DMARDs (tsDMARDs) have been advised to be discontinued in suspected or confirmed cases of COVID-19." (PMID 34943795, 2021). "It is generally known that cytokine storm was associated with the process and the levels of IL-6 and CRP can predict the severity and prognosis of COVID-19 patients." (PMID 33557785, 2021). "This study evaluated the efficacy and safety of specific interleukin (IL)-1 inhibitors, specific IL-6 inhibitors, and GM-CSF blockades in the treatment of COVID-19 (at the edge of sepsis) patients through systematic review and meta-analysis." (PMID 35126138, 2021). "Within COVID-19 patients, only serum IL-6 and IL-10 levels are significantly higher in critical group than in moderate and severe group." (PMID 34064802, 2021). "In COVID-19 patients, IL-6 concentration directly correlated with IL-10 levels (r = 0.48, p < 0.01) and CRP levels directly correlated with N/L ratio (r = 0.37, p = 0.04)." (PMID 33808205, 2021). "Elevations in serum IL-6 levels in patients affected by severe COVID-19 have spurred a renewed interest in this cytokine as a therapeutic target in the broader context of the cytokine storm syndrome triggered by SARS-CoV-2 infection." (PMID 34768455, 2021). "High level of IL-6 was early reported to be correlated with SARS-CoV-2 viral load in the blood of critically ill COVID-19 patients." (PMID 33602326, 2021). "Two inflammatory ILs, interleukin-2 receptor (IL-2R) (p = 0.01) and interleukin-6 (IL-6) (p = 0.001), were found to have relationships with inferior prognosis in patients with COVID-19." (PMID 34970527, 2021). "On the other hand, two randomized controlled trials (ReMAPCap and RECOVERY) showed that blockade of the IL6 pathway with tocilizumab improves the prognosis of COVID-19 patients." (PMID 34884590, 2021). "Normal human serum levels of IL-6 are in the range of 1–10 pg/mL, while levels seen in severely ill COVID-19 patients are on average of 36.7 pg/mL." (PMID 34835296, 2021). "Yesupatham and colleges assessed interleukin-6 and ferritin levels, and their clinical correlations, among COVID-19 patients." (PMID 34831321, 2021). "In a small study, the COVID-19 patients were distinguished based on different complications such as IL-6 mediated ARDS, inflammatory response, co-infection, immune dysfunction due to C-reactive proteins, and hyper-ferritinemia." (PMID 34649460, 2021). "IL-6 is also an important inflammatory cytokine that is elevated during COVID-19 inflammatory condition." (PMID 34195193, 2021). "The cytokines involved in COVID-19 are, among others, interleukins (IL-6, IL-1β, and tumor necrosis factor α), which are believed to be responsible for septic shock and multiorgan failure, including myocardial damage and circulatory failure." (PMID 33687179, 2021).